RNU6-299P (RNA, U6 small nuclear 299, pseudogene)
Gene: Small nuclear RNA gene on chromosome 5 (56,125,671 to 56,125,770, forward strand). Ensembl gene ENSG00000253032.
Homologues: Orthologues: chimpanzee U6 (98% identical), macaque U6 (91% identical), pig U6 (65% identical), dog U6 (64% identical), mouse Gm26017 (59% identical), guinea pig U6 (58% identical), mouse Gm55659 (57% identical), zebrafish U6 (54% identical), rabbit U6 (49% identical). Paralogues in human: RNU6-144P (73% identical), RNU6-836P (73% identical), RNU6-164P (72% identical), RNU6-16P (72% identical), RNU6-812P (72% identical), RNU6-1005P (71% identical), RNU6-1020P (71% identical), RNU6-10P (71% identical), RNU6-1251P (71% identical), RNU6-125P (71% identical), RNU6-15P (71% identical), RNU6-211P (71% identical), and 1286 more.